CRP (C-reactive protein)
Diseases named in the same sentence as CRP in open-access papers (continued):
Sharing a sentence is not in itself a finding about the gene and the disease.
metabolic syndrome (continued). "Some studies describe the association of various laboratory parameters with cardiovascular comorbidity in dialysis patients: C-reactive protein and plasma fibrinogen, as well as the presence of metabolic syndrome." (PMID 40918766, 2025). "CRP is a commonly used inflammatory biomarker, and previous studies have confirmed that CRP levels can influence metabolic syndrome and schizophrenia symptoms." (PMID 40791199, 2025). "For example, curcumin supplementation (500 mg twice daily for 8 weeks) in patients with metabolic syndrome led to significant improvements in endothelial-dependent vasodilation, a reduction in C-reactive protein (CRP), and decreased serum levels of IL-6." (PMID 41002745, 2025). "The CRP/Alb ratio, reflecting both inflammation and nutritional status, has been proposed as a prognostic indicator in metabolic syndrome and liver disease." (PMID 41302334, 2025). "Metabolic syndrome was present in 24% of participants at baseline, with CRP levels rising progressively with the number of metabolic syndrome components." (PMID 40943152, 2025). "This study focused on intermediate outcomes, including dyslipidemia and oxidative stress, and inflammation markers, such as TNF-α, IL-6, and CRP, which predict cardiovascular health risk." (PMID 39840146, 2025). "CRP/HDL-c has been introduced into clinical practice as a potential marker for predicting metabolic syndrome (MetS)." (PMID 40655403, 2025). "The original ABCD score reported by Rinaldi et al13 includes 4 components, such as acute clinical presentation (ie, MINOCA), MB, CRP, and dyslipidemia." (PMID 40373526, 2025). "Research has linked plant-based diets to significantly lower levels of C-reactive protein (CRP), a key inflammatory marker associated with metabolic syndrome and cardiovascular disease risk." (PMID 40362807, 2025). "Children as young as 3 years old demonstrate elevated c-reactive protein (CRP) and absolute neutrophil counts that correlate with many metabolic syndrome mechanisms." (PMID 40422865, 2025). "Conversely, previous studies found that vitamin B12 deficiency is positively associated with inflammatory factors [such as C-reactive protein (CRP) and interleukin 6 (IL-6)], and leads to metabolic syndrome onset and an increase in cardiovascular risk factors." (PMID 40791230, 2025). "An observational study from Korea showed a positive correlation between CRP concentration and metabolic syndrome, as well as significantly higher CRP levels in PTB patients compared to the general population." (PMID 40453733, 2025). "Elevated GDF-15 levels have previously been related to hs-CRP in individuals ≥ 65 years of age with metabolic syndrome." (PMID 39000435, 2024). "The increased CRP levels, a ubiquitous inflammatory marker, align with the understanding that metabolic syndrome constitutes a pro-inflammatory state." (PMID 39202262, 2024). "The beneficial indirect effects of diet quality and nutrient density on NAFLD prevention were mediated by changing WHtR, HBA1c, CRP, and metabolic syndrome." (PMID 39198491, 2024). "For example, a direct comparison of CRP concentrations between normal weight, obese, and metabolic syndrome patients showed elevated concentrations in the obese and metabolic syndrome groups." (PMID 38666038, 2024). "CRP at baseline in patients 2 (7 mg/L) and 3 (8 mg/L) was indicative of low-grade inflammation seen in obese patients with metabolic syndrome." (PMID 39588043, 2024). "For example, a very recent study indicated that 12 weeks of low‐volume HIIT had a greater positive effect on IL‐6 and CRP compared to whole‐body electromyostimulation and resistance training in people with metabolic syndrome." (PMID 39107107, 2024). "Based on the gender-stratified path analysis, in women, diet quality indirectly through WHtR, CRP, and metabolic syndrome, and in men through WHtR, Hemoglobin A1c, and metabolic syndrome affected NAFLD." (PMID 39198491, 2024).
metabolic syndrome (continued). "The aim of this paper is to explore the impact of C-reactive protein, dyslipidemia and the combination of the two on the development of stroke." (PMID 39247228, 2024). "In females, the risk of stroke was found to be 2.41 times higher in the group with abnormal C-reactive protein and dyslipidemia compared to the normal population." (PMID 39247228, 2024). "Intensive treatment should be considered in patients with metabolic syndrome who have elevated CRP levels as the main treatment target." (PMID 39902081, 2024). "Recently, human CRP transgenic SHR-CRP rats were introduced to assess CRP’s role in the pathogenesis of metabolic syndrome." (PMID 38627621, 2024). "Triglyceride and CRP levels were assessed and categorized based on Korean guidelines for dyslipidemia and CDC/AHA guidelines, respectively." (PMID 38167529, 2024). "Nutrient density directly and indirectly in women through WHtR, CRP, and metabolic syndrome, and in men indirectly through WHtR, hemoglobin A1c, and metabolic syndrome negatively affect NAFLD." (PMID 39198491, 2024). "Initially, we examined the temporal relationship between inflammation (high-sensitivity C-reactive protein (CRP)) and metabolic disorders (metabolic syndrome severity Z-score (MetS-Z)) using a 3.98-year survey and cross-lagged analysis." (PMID 38386717, 2024). "Aside from dyslipidemia, elevated CRP levels also exacerbate the atherosclerotic process and increase the risk of the development of cardiovascular diseases." (PMID 39000486, 2024). "Supplementation with alpha-linolenic acid (ALA) on the other hand has also been analyzed with positive results in reducing inflammatory parameters, such as IL-6 (Interleukin-6), CRP (C-reactive protein), and fasting glucose, in subjects with dyslipidemia." (PMID 38605945, 2024). "C-reactive protein (CRP) is an acute inflammatory protein detected in obese patients with metabolic syndrome." (PMID 38627621, 2024). "In particular, the MedDiet proved effective in reducing IL-6 and CRP in individuals with metabolic syndrome compared to controls." (PMID 38613111, 2024). "Markers of metabolic disease (i.e., dyslipidemia, dysglycemia and systemic inflammation) were measured pre and post intervention, including bloods lipids, hemoglobin A1c, and C-reactive protein." (PMID 39771028, 2024). "Compared with those with normal CRP levels and non-dyslipidemia, the adjusted ORs and 95%CI were 1.74 (1.08, 2.78) for the individuals with elevated CRP levels and dyslipidemia, 2.41 (1.29, 4.49) for the male with elevated CRP levels and dyslipidemia." (PMID 39247228, 2024). "Among the group with abnormal C-reactive protein and dyslipidemia, after adjusting for confounding factors, it was found that the risk of stroke in this group was 1.74 times higher than that of the normal population." (PMID 39247228, 2024). "Based on the gender-stratified path analysis, diet quality indirectly through Waist-to-Height Ratio (WHtR), C-reactive protein (CRP), and metabolic syndrome in women, and men through WHtR, hemoglobin A1c (HBA1c), CRP, and metabolic syndrome affects NAFLD." (PMID 39198491, 2024). "Significant higher values were found for anthropometric variables and markers of glucose and dyslipidemia in individuals with higher BMI, as well as elevated levels of C-reactive protein, fibrinogen, IL-6, uric acid, and D-dimer." (PMID 39081294, 2024). "Altered HPA axis can lead to changes in metabolic (e.g., metabolic syndrome (MetS)), cardiovascular (e.g., systolic and diastolic blood pressure and heart rate), and immune systems (e.g., C-reactive protein (CRP) and fibrinogen)." (PMID 40226750, 2024). "Low IGFBP-1, high CRP and low IGF-I are independently associated with the presence of WHO-defined metabolic syndrome and insulin resistance in different ethnic groups (n = 440, mean 51 y, ~50% F)." (PMID 39595651, 2024).
metabolic syndrome (continued). "The indirect relationship between HEI2015 and NAFLD was explained through WHtR, and metabolic syndrome, as well as WHtR, CRP, and metabolic syndrome in women." (PMID 39198491, 2024). "Clinically, high-sensitive C-reactive protein (hs-CRP) is known to be a marker of inflammation and is predictive for myocardial infarction, stroke, and the aggravation of metabolic syndrome." (PMID 38742193, 2024). "Other studies have shown that the CRP levels and dyslipidemia have a synergistic effect on the pathogenesis of CAD, and the association between dyslipidemia and CAD appears to be enhanced by elevated CRP levels." (PMID 39596269, 2024). "The association between GlycA and subclinical CV was maintained after controlling for typical covariates including age, sex, dyslipidemia, smoking, BMI, and even CRP." (PMID 38892172, 2024). "The findings demonstrated that both dyslipidemia and increased hs-CRP levels significantly raised the likelihood of CAD." (PMID 39192929, 2024). "In the entire group of subfertile individuals, a significant correlation between C-reactive protein and the biochemical components of metabolic syndrome was observed." (PMID 37763034, 2023). "This study aimed to assess the interaction of dyslipidemia and high-sensitivity C-reactive protein (hs-CRP) on CVD." (PMID 37403063, 2023). "Our data demonstrated improved parameters of the metabolic syndrome such as weight, BMI z-score, waist circumference, and CRP, as well as improved glycemic control, among adolescents with T1DM following a 6-month LCD intervention." (PMID 36986149, 2023). "A study showed that increased liver enzymes secondary to hepatic steatosis are frequent in metabolic syndrome cases, and there exists a direct link between elevated liver enzymes and CRP levels." (PMID 37873776, 2023). "The fraction of glycated hemoglobin (Hb1Ac) was positively associated with markers of inflammation (C-reactive protein-CRP r = 0.618; p = 0.006) and of dyslipidemia (triglycerides-TG r = 0.815; p < 0.0001)." (PMID 36672627, 2023). "Individuals with Metabolic syndrome present with a pro-inflammatory state, which is recognized by elevated concentrations of C-reactive protein (CRP) levels." (PMID 37521410, 2023). "The intake of piperine was also linked with enhanced antioxidant and anti-inflammatory properties by increasing serum levels of superoxide dismutase while reducing those of malonaldehyde and C-reactive protein in individuals with metabolic syndrome." (PMID 37764345, 2023). "In this study, age, SBP, PP, CRP, TyG, physical performance, history of dyslipidemia, memory-related disease, and ENP problems were independent predictors for new-onset stroke." (PMID 37388187, 2023). "The multiple logistic regression analysis was performed using the GNRI, BI, age, sex, BMI, NYHA functional class III/IV, dyslipidemia, eGFR, CRP, and TP levels as explanatory variables." (PMID 38137731, 2023). "Significant differences were observed between the high and low ADL groups in terms of age, sex, BMI, NYHA functional class III/IV, admission BI scores, dyslipidemia, Cre levels, eGFR levels, Alb levels, TP levels, CRP levels, and admission GNRI scores." (PMID 38137731, 2023). "There is an inverse correlation between serum bilirubin and high sensitive C-reactive protein in patients with metabolic syndrome, lower serum bilirubin levels are involved in enhanced low-grade systemic inflammation." (PMID 36960314, 2023). "Diffuse fatty liver, excessive visceral fat, subcutaneous fat, CRP, and metabolic syndrome correlated with CAD." (PMID 37623840, 2023). "In our previous study in 2020, we evaluated serum uric acid (UA), CRP levels and presence of metabolic syndrome in patients with rosacea." (PMID 37277425, 2023). "There were significant associations between METS-IR, HOMA-IR, and CKD incidence even after adjusting for age, sex, BMI, physical activity, smoking, alcohol drinking, DM, HTN, dyslipidemia, and CRP." (PMID 37957738, 2023).
metabolic syndrome (continued). "On the other hand, the relationship between demographic and clinical factors of patients with ferritin, NLR, and CRP was significant only for CRP and dyslipidemia (P = 0.020)." (PMID 37217858, 2023). "Overall, increased CRP in metabolic syndrome patients increases the likelihood of cardiovascular events (CVE) by its impact on vascular cells, especially monocyte activation and the formation of endothelial cell dysfunction." (PMID 38248733, 2023). "Stroke patients with metabolic syndrome had increased plasma levels of the proinflammatory cytokines CRP, IL-6 and TNF-α but decreased levels of the anti-inflammatory cytokine IL-10 compared to stroke patients without metabolic syndrome and nonstroke patients." (PMID 37587512, 2023). "Based on this, using logistic regression, the relationship between CRP and intubation status was still significant by adjusting the patients’ dyslipidemia status as a confounding variable." (PMID 37217858, 2023). "Our results confirm a higher prevalence of individuals with elevated CRP and fibrinogen among those with airflow limitation and PRISm, particularly in the subgroups with the metabolic syndrome." (PMID 38023334, 2023). "Today, several investigations have established that people with MetS (metabolic syndrome) have high CRP levels." (PMID 38248733, 2023). "So the mean CRP in patients with dyslipidemia was 102.85 ± 50.50 mg/dl; in other patients, it was 85.14 ± 59.14." (PMID 37217858, 2023). "CRP is routinely assessed as a marker of systemic inflammation and RA as well, and it is also lniked to implications such as atherosclerosis and metabolic syndrome." (PMID 36709303, 2023). "It was discussed that mean log hsCRP elevated as the number of components of metabolic syndrome increased, and also that CRP adds clinically important prognostic information to this condition." (PMID 37873776, 2023). "Consistent with previous studies, age, SBP, PP, CRP, and dyslipidemia play important roles in stroke." (PMID 37388187, 2023). "AgeAccelENCen40 + is correlated with markers of inflammation, metabolic syndrome, and C-reactive protein (bicor = 0.08 and P = 8.8 × 10−11) and insulin levels (bicor = 0.09 and P = 1.7 × 10−5)." (PMID 36964402, 2023). "Given that CRP is now considered a biomarker of systemic inflammation and that metabolic syndrome is associated with systemic inflammation, researchers have aimed to assess how periodontitis might impact the onset, development, or progression of metabolic syndrome." (PMID 38132215, 2023). "Other study shows that curcuminoid-piperine coalition markedly improves oxidative and inflammatory state by enhancing SOD activities and reducing concentrations of MDA and plasma C-reactive protein (CRP) in the sick with metabolic syndrome." (PMID 37191432, 2023). "Heightened concentrations of C-reactive protein are directly related to body mass index, abdominal circumference, high blood sugar and resistance to insulin in persons diagnosed with metabolic syndrome." (PMID 38248733, 2023). "Cross-sectional epidemiological studies in humans reveal that the pan-mammalian clocks correlate with markers of inflammation (C-reactive protein) and dyslipidemia (triglyceride levels)." (PMID 37563227, 2023). "In terms of dyslipidemia, B symptoms, molecular typing, BCL2 fusion translation, ferritin, CRP, and IL-6 have influenced dyslipidemia (p <0.05)." (PMID 37384286, 2023). "The intersections of all metabolic syndrome components and elevated high sensitivity C-reactive protein (hs-CRP) were also analyzed." (PMID 37633936, 2023). "In our meta-analysis, we managed to confirm that C-reactive protein (CRP) is a good marker for identifying inflammation in pediatric metabolic syndrome." (PMID 38001962, 2023). "Greater percents of moderate or severe CAL were associated with increased numbers of monocytes, inflammatory markers, like CRP and fibrinogen, and a dyslipidemia profile, with high triglycerides and low HDL levels." (PMID 38292927, 2023).
metabolic syndrome (continued). "According to previous studies, DM history, HTN history, smoking history, dyslipidemia, and sedentary lifestyle are conventional risk factors for PAD,18, 19, 20 while C‐reactive protein (CRP) and LP(a) are inflammatory risk factors for PAD." (PMID 36896666, 2023). "Age, homeostatic model assessment of insulin resistance 1 (HOMA1-IR), HALS, dyslipidemia, C-reactive protein, and CVR estimated with the Framingham score correlated with GDF15 levels." (PMID 35160008, 2022). "This shows that saliva testing for CRP can potentially be used early in life as an alternative and less invasive measure for metabolic syndrome." (PMID 35757631, 2022). "Chronic inflammatory biomarkers, like C-reactive protein (CRP) levels, have been linked with the existence and extent of the metabolic syndrome, preclinical atherosclerosis, and the development of atherosclerosis." (PMID 35732620, 2022). "Taken together, these genes, which were prominent and pleiotropic across CRP and OP, suggest a potential pathway involving metabolic syndrome." (PMID 35349660, 2022). "Chronically elevated levels of CRP are an independent risk factor for several morbidities including CVDs, T2DM, the metabolic syndrome, stress overall frailty, and mortality among the elderly, but are also symptomatic of several of these conditions." (PMID 35035976, 2022). "MR-proADM can also be used as a biomarker for arterial stiffness in patients with metabolic syndrome, its predictive value being superior to that of CRP." (PMID 35563387, 2022). "Numerous studies have shown the positive effect of a high intake of fish and unsaturated fatty acids on the lipid profile, CRP levels, incidence of metabolic syndrome and cardiovascular events." (PMID 35682146, 2022). "In our prior study we investigated serum CRP levels in PA patients, and showed that KCNJ5 mutations were associated with lower levels of pro-inflammation factors, metabolic syndrome and abdominal obesity." (PMID 35311227, 2022). "Inflammation, as reflected by elevated serum CRP, also appears to be involved in cardiovascular morbidity and mortality in people with metabolic syndrome and type 2 diabetes." (PMID 36467859, 2022). "As expected, AgeAccelGrim2 was still associated with age-related biomarkers including inflammation marker CRP (r=0.26 and P=5.5x10-4), dyslipidemia marker triglyceride levels (r=0.23 and P=2.8x10-3), and body mass index (r=0.25 and P=9.1x10-4)." (PMID 36516495, 2022). "The association between RDW and Metabolic syndrome can be explained by increased inflammation, which shows a significant relationship between high RDW and C-reactive protein, white blood cells, and fibrinogen." (PMID 35236423, 2022). "In T2D, CATi was associated with early death or ICU independently from age, sex, BMI, dyslipidemia, CRP and coronary calcium (CAC)." (PMID 36587209, 2022). "Descriptive information regarding child maltreatment, depressed mood, metabolic syndrome, and C-reactive protein (CRP)." (PMID 35910956, 2022). "Eighty-four lead SNPs were associated with 101 CVD-related traits, including chronic kidney disease (n = 18,) C-reactive protein (n = 14), metabolic syndrome (n = 12), body mass index (n = 8), and systolic blood pressure (n = 4)." (PMID 35668104, 2022). "After adjustment for age, sex and BMI in model 1 and for dyslipidemia, CRP, CAC-DRS = 3 (severe coronary artery calcifications) in model 2, CATi remained independently and significantly associated with ICU admission or death (p = 0.005)." (PMID 36587209, 2022). "In our study group, participants with severe OSA (AHI≥30 per hour) more frequently had metabolic syndrome, while those with metabolic syndrome had higher levels of CRP and ESR." (PMID 35694268, 2022). "High sensitivity C-reactive protein (hs-CRP), a marker of systemic inflammation and predictor of T2DM and cardiovascular disease (CVD), has been shown to associate with metabolic syndrome and its components." (PMID 35267891, 2022).